IL17A (interleukin 17A)
Diseases named in the same sentence as IL17A in open-access papers (continued):
Sharing a sentence is not in itself a finding about the gene and the disease.
periodontitis (continued). "Furthermore, inhibition of histones, a major component of NETs, substantially reduces upregulation of IL‐17‐related genes (IL‐17a, S100a9, and IL‐6), decreases IL‐17‐positive cells and Th17 cells accumulation, and subsequently protects against periodontal bone loss in periodontitis." (PMID 41031144, 2025). "This study analyzed a total of twenty‐eight genetic variants corresponding to the IL‐17A: rs 2275913 (68.4%), rs 3819024 (5.3%), rs 10484879 (5.3%); IL‐17F: rs 763780 (47.4%), IL‐17R: rs 879576 (11%) and IL‐23R: rs 11209026 (11%) genes in subjects with periodontitis and peri‐implantitis." (PMID 39887950, 2025). "Therefore, IL-17A−IL-17F+ Th17 cells may also play important role in periodontal disease like IL-17A+IL-17F− Th17 cell as both Th17 cells were correlated with the attachment loss in periodontitis." (PMID 25525302, 2014). "Apparently, the increased levels of IL-17A+IL-17F− and IL-17A−IL-17F+ Th17 cells in CP group correlated with attachment loss and probing depth, indicating there may be potential mechanism for these Th17 cells in periodontitis." (PMID 25525302, 2014). "Most of these studies, including our working group, demonstrate an increase in IL‐23, IL‐17A, and IL‐17RA in GT from patients with periodontitis." (PMID 41536464, 2026). "In the present study, we found a significant increase in IL‐17A expression in periodontitis patients, which agrees with what has been reported by several authors, including our working group, using various techniques." (PMID 41536464, 2026). "We found a significant increase in IL‐23, IL‐17A, IL‐23R, and IL‐17RA protein levels in the periodontitis group compared with the healthy group; we also detected bands with unexpected molecular weights for both receptors." (PMID 41536464, 2026). "Meanwhile, in the group of patients with periodontitis, significant correlations were found between: IL‐23R and IL‐23 [r = 0.469 (p = 0.021)]; as well as between IL‐17RA and IL‐17A [r = 0.713(p < 0.001)] and with IL‐23 [r = 0.637 (p = 0.001)]." (PMID 41536464, 2026). "In this study, we detected overexpression of IL‐23, IL‐17A, and their receptors in GT of patients with periodontitis, confirming that the IL‐23/IL‐17A axis is involved in periodontal disease." (PMID 41536464, 2026). "The involvement of γδ T cells and IL-17A/STAT3 signaling highlights the immunomodulatory effects of periodontitis in OSCC." (PMID 40924302, 2025). "This study analyzed six genetic variations of IL‐17A, IL‐17F, IL‐17R, and IL‐23R genes in people with periodontitis and peri‐implantitis." (PMID 39887950, 2025). "Studies have also shown that genistein significantly reduced the expression levels of TNF‐α, IL‐6, IL‐1β, and IL‐17a in the gingival tissue of periodontitis mice and reduced the damage of inflammatory factors to periodontal tissue." (PMID 40761494, 2025). "We identified a pro-inflammatory signature in GCF of T1DM individuals with periodontitis, marked by elevated IL-1β, IL-6, IL-8, and IL-17A, suggesting activation of both innate and adaptive immune pathways." (PMID 41280935, 2025). "Periodontitis is characterised by a Th17/Treg imbalance, where Th17 cells produce high levels of IL‐17A and RANKL." (PMID 40620009, 2025). "Several studies have shown that levels of IL-1β, IL-6, IL-8, and IL-17A are elevated in periodontal tissues of patients with periodontitis compared to healthy controls, driving disease progression." (PMID 41274884, 2025). "Therefore, not only IL‐17A may have some association with periodontitis or peri‐implantitis." (PMID 39887950, 2025). "Six polymorphisms were evaluated, highlighting rs 2275913 of the cytokine IL‐17A in patients with periodontitis or peri‐implantitis." (PMID 39887950, 2025). "IL-17A-producing γδ T cells were significantly higher in OSCC with periodontitis; inhibiting these cells reduced tumor development, IL-17A, and M2 macrophages." (PMID 40924302, 2025).
periodontitis (continued). "Six polymorphisms were evaluated, the most studied was rs 2275913 of the cytokine IL‐17A in patients with periodontitis or peri‐implantitis." (PMID 39887950, 2025). "Periodontitis is a highly prevalent inflammatory disease characterised by the accumulation of IL‐17A‐expressing CD4+ T cells in response to dysbiotic oral bacterial biofilms, ultimately leading to RANKL‐mediated alveolar bone resorption and tooth loss." (PMID 40620009, 2025). "In periodontitis, γδ T-cells are elevated and stimulate the recruitment of macrophages and neutrophils, as well as the production of pro-inflammatory cytokines like IL-17A and IFN-γ." (PMID 38919613, 2024). "The remaining study examined IL-17A and IL-17E expression in the first 4 weeks of osseointegration among patients with a history of treated aggressive periodontitis and periodontally healthy controls." (PMID 39685706, 2024). "Interleukin-17A (IL-17A) and interleukin-18 (IL-18) are pro-inflammatory cytokines that play important roles in both celiac disease and periodontitis." (PMID 38756445, 2024). "We found that during periodontitis, gingival IL-17 fate-mapped T cells still predominantly produce IL-17A, with little diversification of cytokine production." (PMID 38819409, 2024). "In patients with periodontitis, flow cytometry analyses of blood samples revealed an expansion of IL-17A+IL-17F- and IL-17A-IL-17F+ Th17 cells as compared to healthy controls." (PMID 39253090, 2024). "Salivary interleukin-17A and interleukin-18 levels in patients with Celiac disease and periodontitis." (PMID 38756445, 2024). "Among these cytokines IL-17A and IL-17F have been proposed to play a pivotal role in inflammatory disorders such as chronic periodontitis." (PMID 39253090, 2024). "This is further supported by the observation that in patients with periodontitis and inflammatory bowel diseases, the expression of IL-17A/F and IFN-gamma was significantly increased in gingival tissue in comparison with intestinal mucosa." (PMID 39253090, 2024). "In the same study reporting IL-17A, an elevated level of IL-17A was also observed in the patient group with a history of aggressive periodontitis during osseointegration." (PMID 39685706, 2024). "In an Iranian community, patients with chronic periodontitis had a higher frequency of the IL-17A CC genotype than healthy controls." (PMID 38413570, 2024). "Firstly, studies in experimental models of periodontitis showed that suppression of pro-inflammatory cytokines such as IL-17A or activation of anti-inflammatory cytokines such as IL-10 can ameliorate inflammation and bone loss." (PMID 39253090, 2024). "The application of EV therapy in periodontitis presents significant clinical opportunities by demonstrating how EVs can influence key cytokines like IL-5, IL-6, IL-17A, IL-10, and TNF-α." (PMID 38891939, 2024). "IL-17A and IL-18 levels have been shown to be elevated in the serum and gingival crevicular fluid of periodontitis patients as well as being correlated with periodontal disease clinical manifestations severity." (PMID 38756445, 2024). "Our results did not detect statistically significant differences in IL-17A expression at the mRNA level in the gingival tissue of periodontitis patients and healthy subjects, but IL-17A expression correlated with the proximate plaque index." (PMID 37510729, 2023). "In periodontal pockets of patients with periodontitis, the number of γδ T cells and neutrophils, as well as the expression of IL-17A, are higher than in healthy individuals." (PMID 37623290, 2023). "The pro-inflammatory cytokines IL-6, IL-33 and IL-17A can be proposed as biomarkers of both conditions in GCF due to their ability to trigger the activation of osteoclastogenesis in periodontitis." (PMID 36967976, 2023). "In the first step of our study, we compared the expression of IL-17A and IL-17B at the mRNA level in gingival tissue in patients with periodontitis and control subjects." (PMID 37510729, 2023).
periodontitis (continued). "In mice with periodontitis, the increased Th17-related genes (i.e.,Il6,Il17a, andRorγt), and Treg-related genes (i.e.,Foxp3,Il2,Il10,Ctla4,Cd25, andGitr) were detected in cervical lymph nodes and spleen." (PMID 37226540, 2023). "An animal experiment verified that mice receiving intragastric administration of periodontitis salivary microbiota increased immune cell production of Interleukin-17A in the gut and eventually showed significantly worse stroke outcomes." (PMID 37138888, 2023). "The aim of this study was to examine the expression and localization in gingival tissue of IL-17A and IL-17B in patients with periodontitis." (PMID 37510729, 2023). "It should be pointed out that periodontitis fosters a proinflammatory microenvironment, and the levels of IL-1β, IL-4, IL-10, and IL-17A were significantly higher in diseased sites than healthy sites in the same oral cavity from periodontitis patients." (PMID 36949458, 2023). "IL-17A contributes to neutrophils leaving the bone marrow, entering blood circulation, and reaching the infected site of periodontitis." (PMID 37623290, 2023). "In our study, we examined the expression of IL-17A and IL-17B at the mRNA level, as well as IL-17 protein expression in gingival tissue from patients with periodontitis as well as in healthy subjects." (PMID 37510729, 2023). "In this review, we summarize the recent knowledge regarding oral dysbiosis and its prevention; further, we focus on the role of IL-17A as a pathophysiological mediator in the mechanisms linking periodontitis and systemic inflammatory diseases." (PMID 37623290, 2023). "Yet, in the grade C periodontitis patients, IL17A presented a positive correlation with the periodontal indices, total PPD (r = 0.542; p < 0.01) and CAL (r = 0.583; p < 0.01)." (PMID 36769650, 2023). "This study aims to compare the salivary and gingival crevicular fluid (GCF) concentrations of five cytokines: IL-1β, IL-6, IL-17A, IL-33, and Tumor Necrosis Factor-alpha (TNF-α) in patients with OSA and their association with periodontitis." (PMID 36967976, 2023). "Compared with the AON group, the oral microbiota from periodontitis significantly induced the growth of tumors, the expansion of IL-17+ γδ T cells, and the expression of IL-17A." (PMID 36000726, 2022). "This work aims to provide an overview of the role of IL-17A in the pathomechanisms of periodontitis and related systemic chronic inflammatory diseases and briefly discuss the therapeutic potential of cytokine targeted agents that modulate the IL-17A signaling." (PMID 35371044, 2022). "In accordance with a previous report, we observed that TEM cells accumulated in periodontitis mice display the IL‐17A–producing RORγt+ Th17 phenotype." (PMID 35244953, 2022). "In this work, we review the role of IL-17A in the pathomechanisms of periodontitis and related systemic chronic inflammatory diseases, and briefly discuss the therapeutic potential of cytokine targeted agents that modulate the IL-17A signaling." (PMID 35371044, 2022). "Then we repeated the protocol on Il17a–/– mice to explore the effects of periodontitis salivary microbiota in ischemic stroke." (PMID 35663549, 2022). "The level of IL-17A increased successively in saliva of healthy control group, T2DM patients and T2DM patients with chronic periodontitis, suggesting that the increase of IL-17A is one of the risk factors of chronic periodontitis in T2DM patients." (PMID 35371044, 2022). "ILC3s are also the predominant subset in the periodontal tissue of periodontitis, and they were activated by producing more IL-17A and IFN-γ in comparison with the healthy ones." (PMID 35631034, 2022). "A significant increase in IL-17A was observed after coculture with the live oral microbiota from periodontitis." (PMID 36000726, 2022). "Periodontitis induced generation of oral-pathobiont specific IL-17A+ TH17 memory T cells that accumulated in the cervical lymph nodes." (PMID 34950607, 2021).
periodontitis (continued). "From the immunological point of view, BBR by attenuating the production of TNF‐α and IL‐17, as well as the number of IL‐17A+ cells in the alveolar bone effectively inhibited the local and systemic inflammation in the periodontitis rat model." (PMID 34719112, 2021). "Increasing evidence has shown that T-helper 17 (Th17) cells that produce interleukin (IL)-17 (also known as IL-17A) are involved in the pathogenesis of periodontitis and alveolar bone destruction." (PMID 33981487, 2021). "Compared with the periodontitis group, the levels of IL-17A, IL-10 were downregulated and IL-6,TGF-β1 were upregulated in the SPRC groups." (PMID 35087796, 2021). "Previous reports have shown that inflammatory cytokines IL-17A and IFN-γ are implicated in driving the pathogenesis of periodontitis and consequent bone and tooth loss." (PMID 34381457, 2021). "Remarkably, ILC1s and ILC3s from periodontitis patients produce more IL-17A and IFN-γ than that from healthy controls." (PMID 34381457, 2021). "In a recent study, the expression of Il17a was moderated in the first two days after the periodontitis model was established but increased rapidly in the subsequent days." (PMID 34445604, 2021). "As it relates to the oral cavity, IL-17A has been shown to stimulate the development of osteoclasts (osteoclastogenesis) in the presence of osteoblasts, and expression of IL-17 has been observed in gingiva from patients with periodontitis." (PMID 33763040, 2021). "There were also detectable levels of other inflammatory mediators such as TGF-β1, IL-1β, IL-2, IL-4, IL-10, IL-12p70, and IL-17A in the GCF samples of periodontitis patients." (PMID 34502071, 2021). "Rep-orts indicatethat IL-17A has a key role in the progression of chronic and aggressive periodontitis.IL-17A triggers the proinflammatory cytokines such as TNF-α, IL-6, and IL-1β expressions and promotes neutrophil migration." (PMID 34514065, 2021). "Upon stimulation with IL-23 and IL-1β, the expression of IFN-γ and IL-17A by ILC3s was markedly enhanced in periodontitis patients compared to healthy controls." (PMID 34381457, 2021). "IL-17A induces the expression of RANKL by different cell types during periodontitis, such as osteocytes, osteoblasts and periodontal ligament cells, which in turn increase the local net RANKL production and induced further bone loss." (PMID 33149125, 2020). "This suggests that whole salivary assessment of IL-17A and IL-23 can be used as a biomarker of periodontitis especially among tobacco-smokers and recreational-drug smokers." (PMID 33066031, 2020). "Current research suggests that in periodontitis Th17 cells and their signature cytokine, IL-17A, are central to bone destruction by promoting osteoclastogenesis." (PMID 32391008, 2020). "In the context of periodontal disease, we do not know if CD3+ DN T cells are contributing to host defense or exacerbating periodontitis by acting as an additional source of IL-17A." (PMID 32391008, 2020). "Several previous meta-analyses bring results on the possible association among polymorphisms in IL1A, IL1B, IL6, IL10 and IL17A/F genes and diverse clinical aspects of periodontitis, as well as dental implant failure." (PMID 32075624, 2020). "At the gingival tissues, a significant increase in the mRNA levels of Th17-related genes -such as IL-6, IL-17A, and Rorγt- were detected early at five days, and reaching its maximum at ten days post-periodontitis induction (≈ 10–20 fold-change)." (PMID 33149125, 2020). "In general, there is a clear consensus that expression of IL-17A and IL-23 in oral fluids (UWS and gingival crevicular fluid [GCF]) is associated with the etiopathogenesis of periodontitis." (PMID 33066031, 2020). "The present study aimed to investigate the roles of IL-17A and IL-18 in periodontitis and DM by measuring salivary and serum levels, respectively." (PMID 32053656, 2020).
periodontitis (continued). "Accordingly, we detected a significant increase in the percentage of IL-17A+ Tregs after periodontitis induction, particularly at day 10 (p < 0.01), which correlated to their increased absolute cell number (p < 0.05)." (PMID 33149125, 2020). "IL-17A is the most studied member of the Th17 cytokine family and its overproduction was related to autoimmune diseases and chronic inflammation, including periodontitis." (PMID 32053656, 2020). "Interleukin (IL)-17A and IL-18 have been proposed to play important roles in periodontitis and type 2 diabetes mellitus (DM), but human data are conflicting." (PMID 32053656, 2020). "The IL-17 family, consisting of IL-17A–IL-17F, plays an important role in host defense against microbial challenge and has also been demonstrated to be crucial in pathogenesis of periodontitis." (PMID 30837987, 2019). "Periodontitis patients exhibit lower IL-17E serum levels and the IL-17A-IL-17E ratio in serum also correlates positively with clinical parameters." (PMID 30837987, 2019). "According to their studies serum, saliva and GCF IL-17A levels are increased in periodontitis patients and correlate with the clinical parameters attachment loss, pocket depth and bleeding on probing." (PMID 30837987, 2019). "Among the CD4+ T-cell subsets, TH17 cells exclusively accumulated in the oral mucosa and draining lymph nodes during oral infection, consistent with high expression of TH17-related cytokines Il17a and Il6 in the oral mucosa of periodontitis-induced mice." (PMID 29453398, 2018). "Two studies have shown that gingival γδ T cells produce IL-17A; global IL-17A production is a major driver of periodontitis." (PMID 30279177, 2018). "IL1alpha, IL1beta and IL17A, and their ratios with IL2, are excellent diagnostic biomarkers in GCF for distinguishing periodontitis patients from periodontally healthy individuals." (PMID 30573746, 2018). "The outstanding predictive accuracy of the resulting smoking-adjusted models showed that IL1alpha, IL1beta and IL17A in GCF are very good biomarkers for distinguishing patients with chronic periodontitis from periodontally healthy individuals." (PMID 28912468, 2017). "In Czech periodontitis patients, IL-17A −197 AA + AG carriers had higher IL-17 levels in unstimulated mononuclear cells than GG homozygotes." (PMID 26924897, 2016). "A case-control study was conducted on patients with chronic periodontitis (CP) and healthy controls with the aim of evaluating possible association between interleukin 17A (IL17A) G197A (rs2275913) and IL17F T7488C (rs763780) polymorphisms and periodontitis." (PMID 26339129, 2015). "IL17A AA genotype was more frequent in patients with chronic periodontitis (CP) in the codominant and recessive models (P = 0.09; OR = 2.53 and P = 0.03; OR = 2.46, resp)." (PMID 26339129, 2015). "In our previous studies of periodontitis pathogenesis, we found that serum IL-17A level was elevated in periodontitis patients than healthy controls." (PMID 25525302, 2014). "This is in line with studies showing increased serum concentrations of IL-17A, mainly for patients with aggressive periodontitis." (PMID 23304063, 2012). "Therefore, the aim of this study was to quantify the expression of the IL‐23/IL‐17A axis using the western blotting (WB) technique in GT samples from patients with periodontitis." (PMID 41536464, 2026). "Similarly, IL‐17A (15 kDa) expression was significantly higher in periodontitis patients (median 0.789, IQR 1.860) compared with healthy subjects (median 0.00, IQR 0.363; p = 0.002)." (PMID 41536464, 2026). "In the paper that compared cytokine levels for 54 periodontitis patients and 40 healthy controls, cytokines IL‐1β, IL‐4, IL‐6, IL‐10, IL‐17A, IL‐17F, IL‐21, IL‐22, IL‐23, IL‐25, IL‐31, IL‐33, IFN‐γ, sCD40L and TNF‐α were measured in saliva and serum at baseline, 3, 6 and 12 months after treatment." (PMID 41580300, 2026).